MFN2 (mitofusin 2)
Diseases named in the same sentence as MFN2 in open-access papers (continued):
Sharing a sentence is not in itself a finding about the gene and the disease.
depression (13 papers, 2020 to 2025). "For example, research has uncovered a significant link between Mitofusin-2 (MFN2) in the nucleus accumbens (NAc) and the regulation of anxiety and depression-like behaviors." (PMID 39894345, 2025). "Based on the IL-6-PGC1α-MFN2 pathway, this study explored the correlation between acute hyper-hypoxia and the occurrence and development of depression, which concluded that acute hyper-hypoxia aggravates the symptoms of depression." (PMID 39135980, 2024). "Liu and Zhou also found that Mfn‐1 and Mfn‐2 expression decreased in the brains of rats with chronic mild unpredictable stress and glucocorticoid‐induced depression." (PMID 39639753, 2024). "Acute hyper-hypoxia plays an important role in the development of depression via the IL-6/PGC1α/MFN2 signaling pathway." (PMID 39135980, 2024). "The purpose of this study is to elucidate the role of peroxisome proliferator-activated receptor gamma coactivator 1-alpha (PGC1α)/mitofusin-2 (MFN2) signaling axis in the development of depression in mice under hypoxia." (PMID 39135980, 2024). "Experimental study showed that Mfn2-mediated mitophagy activation played a significant role in mitigating depression-like behaviors in hypertension rats." (PMID 39611132, 2024). "The aims of this study were to investigate the effects of hypoxia on the development of depression in mice and to clarify the involvement of the PGC1α/MFN2 signaling axis." (PMID 39135980, 2024). "For example, mitochondrial molecules MFN2 in brain has been shown to regulate anxiety and depression-like behavior through actions on mitochondrial in rat model." (PMID 37344456, 2023). "Regarding the depression-like behaviors, Mfn2 downregulation decreased pleasure and enthusiasm and increased behavioral despair." (PMID 36765376, 2023). "Collectively, we determined that Mfn2 was the therapeutic target of MOOs to modulate mitophagy activation in the astrocytes during hypertension with depression." (PMID 36765376, 2023). "Mfn2 mediated the anti-depressive role of MOOs with the PI3K/Akt/mTOR pathway during hypertension with depression." (PMID 36765376, 2023). "In hypertension complicated with depression, astrocytes trigger neuroinflammatory responses due to mitochondrial damage, and MOOs upregulate Mitofusin 2 (Mfn2) expression, activating mitochondrial autophagy via the PI3K/Akt/mTOR pathway to clear damaged mitochondria in astrocytes." (PMID 40936908, 2025). "It is speculated that the down regulation of MFN2 may play a significant role in the mitochondrial theory of depression." (PMID 39323965, 2024). "Interestingly, in rodents, it was reported that Mfn2 expression is downregulated in the NAc of outbred rats, which show depression‐like and anxiety‐like behaviors." (PMID 38334212, 2024). "Possibly, Mfn2 downregulation disrupted the balance between the formation and degradation of mitochondria, ultimately resulting in mitochondrial damage in the astrocytes during hypertension with depression." (PMID 36765376, 2023). "Therefore, Mfn2 can be a potential target to improve glia-induced mitochondrial dysfunction during depression progression." (PMID 36765376, 2023). "Mfn2 inhibition partly reversed the effects of MOOs on hypertension with depression." (PMID 36765376, 2023). "Also, acute hyper-hypoxia reduced protein levels of PGC1α and MFN2 RNA in the hippocampal tissues of mice, which confirmed that acute hyper-hypoxia can aggravate the symptoms of depression via a mechanism that is closely related to changes in PGC1α and MFN2 contents." (PMID 39135980, 2024). "In conclusion, acute hyper-hypoxia can regulate the IL-6-PGC1α-MFN2 signaling pathway, aggravate inflammation, influence mitochondrial biogenesis and fusion, damage hippocampal neurons, reduce cognition, memory, and emotional regulation, and accelerate the occurrence and development of depression." (PMID 39135980, 2024). "Hence, Mfn2 is the potential therapeutic target in hypertension with depression." (PMID 36765376, 2023).
depression (continued). "We found MOOs upregulated Mfn2 expression to activate the PI3K/Akt/mTOR pathway-mediated mitophagy, which removing impaired mitochondria in astrocytes during hypertension with depression." (PMID 36765376, 2023). "We did not observe changes in the expression of mitofusin 2 in any of the animal groups studied, which suggests that there are no changes in the mitochondrial fusion process in the model of depression applied in this study or in animals with hypothyroidism." (PMID 33343282, 2020).
diabetic cardiomyopathy (13 papers, 2021 to 2025). Diabetic cardiomyopathy is a disorder of the heart muscle in people with diabetes. "Similarly, diabetic mouse hearts exhibited reduced expression of Mfn2 alongside increased mitochondrial fission, which was associated with impaired mitochondrial function and diabetic cardiomyopathy." (PMID 41382274, 2025). "Decreased MFN2 expression and excessive mitochondrial fission were also observed in diabetic mice and promoted the development of diabetic cardiomyopathy, indicating mitochondrial dynamics is therapeutic target for intervention in diabetic cardiomyopathy." (PMID 36093152, 2022). "For instance, it has been reported that downregulation of Mfn2 imbalances mitochondrial dynamics, contributing to the progression of diabetic cardiomyopathy." (PMID 34744731, 2021). "Rocha, A. G., and their team discovered that delivering a Mitofusin 2 (MFN2) agonist using the mitochondria-targeted peptide SS-31 restores mitochondrial fusion in diabetic cardiomyopathy (fission/fusion ratio decreased by 60%), resulting in a doubled mPTP opening threshold." (PMID 41427043, 2025). "Downregulation of Mfn2 exacerbates diabetic cardiomyopathy, and recent studies have shown that brain natriuretic peptide (BNP) protects against diabetic cardiomyopathy by promoting OPA1-mediated mitochondrial fusion through activation of the PKG-STAT3 pathway." (PMID 41000071, 2025).
ischemia (13 papers, 2018 to 2025). A hypoperfusion of the BLOOD through an organ or tissue caused by a PATHOLOGIC CONSTRICTION or obstruction of its BLOOD VESSELS, or an absence of BLOOD CIRCULATION. "Our in vitro results showed that cordycepin enhanced Mfn2-medicated mitochondrial fusion, improved mitochondrial function, and reduced cardiomyocyte apoptosis in high-glucose/high-fat cultured simulated ischemia/reperfusion cardiomyocytes." (PMID 34744731, 2021). "We found that Mfn2 was highly sensitive to ischemia, decreasing by 60% after 30 minutes of global ischemia in isolated hearts." (PMID 32453773, 2020). "IXA also blocked the release of cytochrome c observed in ischemia and significantly preserved mitofusin-2 integrity." (PMID 32453773, 2020). "Overall, the Opa1 and Mfn2 levels were intended to be lower in hyperglycemic ischemia than in normoglycemic ischemia and deletion of UCP2 affected these fusion markers in normoglycemic ischemic mice." (PMID 33061796, 2020). "Nevertheless, different studies found that constitutive cardiomyocyte-specific Mfn2-deficient mice have improved cardiac recovery after longer I/R (30 min of ischemia + 2 h of reperfusion) and that Mfn2 in vitro overexpression is sufficient to induce apoptosis in cardiac cells." (PMID 35406729, 2022). "Genipin also demonstrated the ability to regulate the imbalance in mitochondrial dynamics induced by ischemia-reperfusion by attenuating the alteration in the protein levels of dynamin-related protein (Drp1) and mitofusin 2 (Mfn2) induced by hepatic ischemia-reperfusion." (PMID 35883477, 2022). "Interestingly, in both in vivo and in vitro found that after myocardial cells experienced ischemia, glucose deprivation and hypoxia, the expression of Mfn2 was significantly upregulated, leading to an increase in mitochondrial fusion proteins and subsequent myocardial and mitochondrial damage." (PMID 40799639, 2025). "Our observations from the present study indicate that augmented expression of CA1 MFN2 was localized to CA1 astrocytes, and in vitro, an early (3 h) increase in miR-200c in response to simulated ischemia was limited to CA1 and cortical astrocyte cultures." (PMID 36466801, 2022).
Cognitive impairment (12 papers, 2016 to 2026). Abnormal cognition is characterized by deficits in thinking, reasoning, or remembering. "Of the top 10 most significant proteins, six (PLOD1, MFN2, NGFR, PPP2R5E, C4A/C4B, and ITGAV) have previously been linked to AD and/or cognitive function, underscoring their potential as biomarkers of cognitive impairment." (PMID 42253369, 2026). "MFN2 overexpression effectively reversed sevoflurane-induced neuronal apoptosis and cognitive deficits." (PMID 40914484, 2025). "Cannabidiol enhances the level of mitofusin 2 (Mfn2), a mitochondrial fusion protein, and improves mitochondrial function in microglia, therefore mitigating neuroinflammation-induced cognitive impairment." (PMID 36203194, 2022). "Our previous studies demonstrate that an increased expression level of Mfn2 positively correlates with oxidative stress in cybrid cells containing mild cognitive impairment (MCI)-derived mitochondria." (PMID 27535796, 2016). "Moreover, repeated ketamine anesthesia similarly reduced MFN2 expression in hippocampal neural stem cells, leading to impaired synaptic plasticity and long-term cognitive deficits." (PMID 40914484, 2025). "Therapeutic strategies designed to improve MAMs through the MFN2 pathway might be a promising approach to prevent cognitive impairment induced by CCH." (PMID 35370565, 2022). "The loosened MAMs and the low expression levels of MFN2 detected in CCH rats might suggest a mechanism that induces cognitive impairment." (PMID 35370565, 2022).
pulmonary fibrosis (12 papers, 2019 to 2026). Chronic progressive interstitial lung disorder characterized by the replacement of the lung tissue by connective tissue, leading to progressive dyspnea, respiratory failure, or right heart failure. "Our previous study revealed that Mfn2 possesses significant potential to inhibit the progression of ARDS-associated pulmonary fibrosis." (PMID 41329539, 2025). "Decreased levels of the mitochondrial fusion protein MFN2 imply a weakened mitochondrial fusion capacity, and studies have shown that the loss of MFN2 leads to aggravation of pulmonary fibrosis." (PMID 36355118, 2022). "Loss of MFN1, MFN2 or inhibiting lipid synthesis via fatty acid synthase deficiency in AEC2 cells exacerbates bleomycin-induced lung fibrosis." (PMID 31358769, 2019). "Our findings suggest that the miR-93-5p/Mfn2 axis may be an important signaling pathway involved in the pathological process of ARDS-associated pulmonary fibrosis." (PMID 41329539, 2025). "Collectively, the marked upregulation of purine metabolism in Mfn1/2−/− AEC2 cells and in bleomycin-treated Mfn1- or Mfn2-deficient AEC2 cells may play a direct role in promoting lung fibrosis, and the pathogenic role of AEC2-specific purine metabolism warrants future investigation." (PMID 31358769, 2019). "Of greater significance, Mfn2 also plays a crucial role in mitigating the progression of pulmonary fibrosis in ARDS." (PMID 41329539, 2025). "In conclusion, the inhibition of miR-93-5p upregulated Mfn2 expression and attenuated ER stress, consequently ameliorating pulmonary fibrosis in ARDS rats." (PMID 41329539, 2025). "Our previous studies has demonstrated that Mfn2 is downregulated in the lung tissues of ARDS mice, and overexpression of Mfn2 can alleviate pulmonary fibrosis, suppress the proliferation of lung fibroblasts, and decrease collagen production in ARDS mice." (PMID 41329539, 2025). "Our previous study demonstrated that the upregulation of Mfn2 can inhibit pulmonary fibrosis in ARDS mice." (PMID 41329539, 2025). "Previous studies have indicated that the absence of mitochondrial fusion proteins mitofusin 1 (Mfn1) and mitofusin 2 (Mfn2) in murine AT2 cells results in spontaneous lung fibrosis." (PMID 39676102, 2024). "In the bleomycin-induced lung fibrosis model, we found increased common genes which were regulated in both Mfn1−/− and Mfn2−/− AEC2 cells." (PMID 31358769, 2019). "Deletion of either Mfn1 or Mfn2 in murine AEC2 cells aggravated bleomycin-induced lung fibrosis, while deletion of both induced spontaneous lung fibrosis." (PMID 31358769, 2019). "Consistently, such distinct functions of MFN1 and MFN2 are highlighted by the observation that Mfn2iΔAEC2 mice develop more severe lung fibrosis than the Mfn1iΔAEC2 mice." (PMID 31358769, 2019). "Our results demonstrated that MFN2 expression was downregulated after coal dust exposure, accompanied by MAMs impairment, Ca2+ imbalance, and increased apoptosis, which ultimately drove the pathological progression of pulmonary fibrosis." (PMID 42198516, 2026). "Moreover, MFN2 plays a role in cell proliferation, apoptosis, and autophagy, contributing to fibroproliferative diseases (such as pulmonary fibrosis, cirrhosis, and cardiovascular fibrosis), atherosclerosis, pulmonary hypertension, tumors and other diseases." (PMID 40177356, 2025). "MFN1 and MFN2 knockout aggravates bleomycin-induced pulmonary fibrosis in mice." (PMID 40559960, 2025). "It is proposed that miR-93-5p may contribute to lung injury and pulmonary fibrosis in ARDS rats by down-regulating Mfn2 through direct targeting." (PMID 41329539, 2025). "Furthermore, we observed that upregulation of Mfn2 expression promotes mitophagy in the lung tissues of mice with ARDS-associated pulmonary fibrosis, thereby impeding the progression of pulmonary fibrosis." (PMID 41329539, 2025).
pulmonary fibrosis (continued). "Besides, MFN2 overexpression in fibroblasts promotes apoptosis, reduces activity, and inhibits proliferation and collagen synthesis, potentially limiting pulmonary fibrosis." (PMID 40177356, 2025). "We reveal that MFN1 or MFN2 deficiency abolishes the lipogenic metabolic response in AEC2 cells under bleomycin-induced mitochondrial damage and demonstrate that impaired regulation of lipid metabolism in the Mfn1/2iΔAEC2 mice drives lung fibrosis." (PMID 31358769, 2019). "Single-gene deletion of Mfn1 or Mfn2 in AEC2 cells exacerbated bleomycin-induced lung fibrosis, but at baseline did not cause any obvious lung pathology." (PMID 31358769, 2019). "Therefore, we hypothesized that miR-93-5p may contribute to the development of ARDS-related pulmonary fibrosis by targeting Mfn2." (PMID 41329539, 2025). "However, it remains to be determined whether the mechanism by which Mfn2 influences lung fibrosis progression in ARDS is mediated through the regulation of ER stress." (PMID 41329539, 2025). "Therefore, miR-93-5p may play a regulatory role in pulmonary fibrosis in ARDS rats by targeting Mfn2; however, this hypothesis requires further validation through in vitro cellular experiments." (PMID 41329539, 2025). "Consequently, we hypothesized that Mfn2 may inhibit pulmonary fibrosis through the alleviation of ER stress." (PMID 41329539, 2025). "Importantly, deletion of Mfn1 or Mfn2 in murine AEC2 cells promotes experimental lung fibrosis and simultaneous deletion of Mfn1/2 in AEC2 cells not only impairs basal surfactant phospholipid and cholesterol metabolism but also leads to the development of spontaneous lung fibrosis." (PMID 31358769, 2019). "To further explore the molecular mechanism by which Mfn2 participates in regulating the formation of pulmonary fibrosis in ARDS, we utilized online prediction tools to analyze potential miRNAs targeting Mfn2 upstream." (PMID 41329539, 2025). "RESULTS: This study revealed that CAMKK2 expression was significantly downregulated in pulmonary fibrosis, concomitant with impaired mitochondrial function-related proteins (PGC-1α, MFN1and MFN2)." (PMID 41053564, 2025). "Here we uncover a critical function for MFN1 and MFN2 in AEC2 lipid metabolism and development of lung fibrosis." (PMID 31358769, 2019). "The differential roles of MFN1 and MFN2 in AEC2 function regulation and lung fibrosis development require further exploration." (PMID 31358769, 2019). "The absence of MFN2 also increases vascular permeability and promotes fibroblast proliferation and collagen synthesis, contributing to pulmonary fibrosis." (PMID 40177356, 2025). "Additionally, deficiencies in the mitochondrial fusion proteins mitofusin 1 (MFN1) and mitofusin 2 (MFN2) can damage lipid metabolism in mouse AT2 cells, affecting surfactant lipid production and promoting the formation of spontaneous pulmonary fibrosis." (PMID 38625722, 2024). "In the bleomycin-induced lung fibrosis model, we did not observe that Mfn1−/− or Mfn2−/− AEC2 cells had significantly increased cell death 5 days after bleomycin administration." (PMID 31358769, 2019). "Subsequently, in vivo experiments revealed a negative correlation between Mfn2 expression and miR-93-5p levels in ARDS rats with pulmonary fibrosis." (PMID 41329539, 2025).
Hypertension (11 papers, 2015 to 2025). The presence of chronic increased pressure in the systemic arterial system. "A more recent Chinese study identified polymorphisms in HSG (also known as Mfn2), a gene involved in mitochondrial fusion and vascular smooth muscle cell homeostasis, as risk factors for essential hypertension." (PMID 41573461, 2025). "Although studies have focused on the relationship between MFN2 gene polymorphisms and many diseases, such as essential hypertension and axonal Charcot-Marie-Tooth disease (CMT2), its correlation with ALF remains unknown." (PMID 28513770, 2017). "Recently, Mfn2 has been reported to be an important biomarker and therapeutic target molecule for cardiovascular diseases such as hypertension." (PMID 26942197, 2016). "We found that Mfn2 levels were increased in the paraventricular nucleus of hypertensive rats compared to controls, indicating that hypertension promotes mitochondrial fusion." (PMID 27713551, 2016). "Recent research demonstrates that Mfn2 could be an important biomarker and therapeutic target molecule for cardiovascular diseases such as hypertension." (PMID 26942197, 2016).